IL10 (interleukin 10)
Diseases named in the same sentence as IL10 in open-access papers (continued):
Sharing a sentence is not in itself a finding about the gene and the disease.
infection (4,407 papers, 2004 to 2026). The state of being infected such as from the introduction of a foreign agent such as serum, vaccine, antigenic substance or organism. "Perhaps most promisingly, emerging biomarkers-particularly interleukin-6, interleukin-10, and procalcitonin-have substantially enhanced our ability to stratify infection risk, demonstrating sensitivity exceeding 85% for bacteraemia detection." (PMID 42042690, 2026). "While β2AR activation enhances IL-10 secretion, limiting early inflammation, prolonged IL-10 elevation contributes to immune exhaustion and increased infection risk." (PMID 40421209, 2025). "For example, the regulation of IL-6 production and TNF signalling were intricately linked to infection, while IL-10 was associated with reduced severity." (PMID 40643149, 2025). "In rodent models of Leishmania infection, males show increased susceptibility to infection, characterized by larger lesions and higher levels of Th2-associated cytokines such as IL-4, IL-10, and TGF-β, along with increased eosinophil recruitment." (PMID 40794782, 2025). "This Breg expansion is associated with reduced IFNγ/IL10 ratio, reduced TNFα production and impaired activation of myeloid cells, likely compromising the innate response to infection." (PMID 41191641, 2025). "The infection caused by Eimeria significantly increased the mRNA expression levels of the IL-10 gene." (PMID 41479898, 2025). "MARCH1 deficiency increased CD86+ DC populations and IFN-γ and IL-10 levels in C57BL/6j mice at day 4 after infection with P. yoelii YM, leading to improved host survival." (PMID 39847577, 2025). "CD4-depleted infected μMT-/- mice exhibited reduced IL-10 and rapid weight loss, succumbing to infection by day 6 after CD4 neutralization." (PMID 40972121, 2025). "To understand the influence of Tr1 cells on the systemic response to infection, we quantified the abundance of Tr1-associated molecules (granzyme A, IFNγ, IL-10, and LAG3) in plasma from the same blood samples used to study CD4+ T cells as a part of MUSICAL." (PMID 41000872, 2025). "It contributes to protection from infection, while the Th2 immune response, characterized by the production of IL-4, IL-10, TGF-β, IL-6, and others, is associated with disease progression and with parasite growth." (PMID 40666521, 2025). "In the case of avian coccidiosis, infection with Eimeria triggers the expansion of Tregs, which is associated with increased expression of IL-10, TGF-β, and CTLA-4." (PMID 40390138, 2025). "These organelles are sites of prostaglandin (PG) E2 synthesis, playing an important role in infection susceptibility by inhibiting NO production and promoting IL-10 release." (PMID 41156732, 2025). "IL-10, predominantly produced by Th2 cells, is a multifunctional anti-inflammatory cytokine associated with immune regulation, defense, and infection." (PMID 39996075, 2025). "It is worth mentioning that LD-R-infection has been reported to induce high levels of IL-10, which is linked with enhanced fluid-phase endocytosis." (PMID 40424189, 2025). "While the Th1 response is associated with host resistance to the parasite, the Th2 response through the expression of IL-4, IL-6, and IL-10 is associated with greater susceptibility to infection." (PMID 40572185, 2025). "A linear regression analysis was performed to evaluate the association between HAdV-36 infection and levels of IL-10, IL-2, IL-6, IL-8, and TNF-α." (PMID 40284995, 2025). "We found that 17ZR101-infection was associated with higher Il10 mRNA expression in infected lungs, especially in infected Tregs and MDSCs." (PMID 40096073, 2025). "They findings further suggested the adoption of clinically associated IL-10 measurements as a criterion for curing the infection." (PMID 38422344, 2024). "The infection of macaques with HTLV-1WT or HTLV-1p12KO was associated with higher plasma levels of IL-10 after 21 weeks, while IL-6, IFN-γ, IL-18, and IL-1β were only elevated in animals infected with HTLV-1WT." (PMID 38668247, 2024).
infection (continued). "Compared to the low level of IL-10 secretion observed with the Bep-deficient strain ΔbepA-G (<50 pg/mL), infection with the ΔbepA-G strain complemented with wild-type BepD resulted in a significant increase in IL-10 secretion." (PMID 39531410, 2024). "The SA infection of IL-10-deficient mice demonstrated that a low IL-10 concentration results in diminished skin lesions and reduced bacterial burden." (PMID 38786139, 2024). "On the other hand, IL-10, a key immunosuppressive mediator, causes corruption of antibacterial immunity, leading to loss of infection control and infection-associated mortality." (PMID 38413535, 2024). "The interplay between Th1 and Th2 immune response was proven to be central in the infection caused by this mycoplasma, where IL-8 and IL-10 stood out as the main cytokines involved in EP." (PMID 38731294, 2024). "IL-10 induction during Sa infection is associated with the inhibition of protective CD4+ T cell development, allowing for Sa reinfections." (PMID 39680460, 2024). "IL-10 has been implicated in the ability of M.tb to evade immune responses and mediate long-term infection owing to its anti-inflammatory role." (PMID 39257584, 2024). "The susceptibility to the infection is strongly dependent upon the finely tuned balance between IL-10 and INF-γ expression." (PMID 39359727, 2024). "Under in vivo conditions, at 72 hours and 2 weeks post-infection, results regarding IL-10+ MDSCs were similar between WT and TLR2-deficient mice." (PMID 39035356, 2024). "Among the subclasses, IgG 1, IgG 2 ang IgG 4 levels were negatively associated with IL-6 concentration, and were positively associated with IL-10 concentration in maternal peripheral plasma at the first infection." (PMID 39495782, 2024). "It was found that BALB/c mice are more susceptible to infection with strong IL-10 response from CD19+ B cells than C57BL/6 mice indicating the role of regulatory B cells toward susceptibility." (PMID 36778886, 2023). "Collectively, these observations indicate that HylB promotes immune suppression in a TLR2/4- and IL-10-dependent manner to enhance the invasive potential of GBS during pregnancy-associated infections." (PMID 37747229, 2023). "The timing of this switch is important for balancing the response to infection and immunopathology: a series of studies from the Lenz group and others have shown that NK cell‐derived IL‐10 makes mice more susceptible to infection if produced too early." (PMID 36861806, 2023). "Collectively, these results suggest that HylB-mediated immune suppression of TLR2/4 is associated with increased rates of IL-10+ macrophages in uterine tissues, which promotes ascending infection." (PMID 37747229, 2023). "A significant decrease in the number of correlations involving IFN-γ detected after infection was diagnosed in susceptible dogs, whereas similar participation of IL-10 was observed both before and after infection." (PMID 37860064, 2023). "Secretion of IL-10 by T cells can influence immune activation early in infection, leading to susceptibility to uncontrolled major infection." (PMID 38149009, 2023). "Activated alveolar macrophages and lymphocytes secrete IL‐6, IL‐10, and chemokines, causing neutrophils to migrate to infection sites." (PMID 37249293, 2023). "Even though the production of IL-10 was blocked in mice, the mortality caused by E. coli JE 5505 infection remained at high levels, as did the cytokines in their serum and the organ damage, compared with E. coli DH5α-infected mice." (PMID 36916913, 2023). "Although, several mechanisms are involved in that process, studies implicate a disproportionately high interleukin (IL)-10 secretion to be associated with host tolerance to infection." (PMID 37637102, 2023). "Elevated levels of IL-10 have been observed in individuals with active TB and have been linked to disease progression, increased bacterial load, and impaired control of the infection." (PMID 38137331, 2023).
infection (continued). "The expression of IL-10 was up-regulated at the late stage (24 to 48 hpi) in PRRSV-associated infection groups, of which the expression of IL-10 was the highest in PRRSV–PCV2 group." (PMID 36992486, 2023). "Studies show that host cells infected with C. trachomatis release pro-inflammatory cytokines throughout their growth cycle, which together with IL-1b, TNF, and IL-10, are associated with poorer prognosis of the infection." (PMID 36897879, 2023). "This emphasized that the involvement of IL-10 and IL-6 in the immune response of channel catfish plays a key role in assisting with organism protection against pathogenic infections as well as tissue repair." (PMID 37513733, 2023). "Infection of IL-10 deficient mice confirmed that the ability of aerobic metabolism to regulate levels of IL-10 plays a key role in the ability of S. pyogenes to modulate levels of tissue damage." (PMID 37384800, 2023). "The results of these studies demonstrated that at 12 weeks post-infection, the lung cells of B cell-deficient μMT mice generate IL-10, upon PPD stimulation, at a level higher than that of WT animals (an increase of 42.8% compared to WT mice; p<0.05)." (PMID 36888692, 2023). "Dysregulation of pro-inflammatory cytokines (TNF-α, IL-1β and IL-6) and anti-inflammatory cytokines (IL-10) are often associated with life-threatening infection or presence of endotoxin." (PMID 37424774, 2023). "The allele C of SNP rs1800871 of IL-10 gene was associated with a decrease risk of bearing high infection intensities in a recessive model (Z = −3.3, P = 0.0009)." (PMID 36889485, 2023). "Further confirmatory studies are needed to evaluate the association between IL‐10 and infection in AH." (PMID 37125245, 2023). "As example, IL-10-deficient mice develop colitis and during infection with T. cruzi and T. gondii succumb to an excessive, lethal inflammatory response." (PMID 37359549, 2023). "IL-10 plays an important role as an anti-inflammatory cytokine by preventing pathogenic infection and excessive immune response, and IL-4 regulates the immune responses." (PMID 37006463, 2023). "Low expression of IFN‐γ (by standard QFM and multiplex), IL‐10, and IL‐23 was associated with incident infection (115 vs 27 IU/mL, P = 0.037; 457 vs 202 pg/mL, P = 0.008; and 1039 vs 663 pg/mL, P = 0.01, respectively)." (PMID 37125245, 2023). "A study showed that infection with multiple species of worms promoted accumulation of IL-10 and TGF-β and caused down modulation of Th1 and Th2 response, resulting in immune hypo-responsiveness." (PMID 37020538, 2023). "IL-10 is a cytokine that contributes to limiting tissue damage caused by infection and a variety of inflammations." (PMID 36601262, 2022). "The cytokine pattern of EBV-HLH is similar to what we have reported previously while patients with infection-associated HLH caused by other pathogens present higher IL-6 but moderately increased IL-10 and IFN-γ." (PMID 35296096, 2022). "IL-10 is a regulatory cytokine that targets the immune system and controls the immune response to reduce tissue damage caused by various pathogen infections (Ouyang and O’Garra., 2019)." (PMID 36310865, 2022). "Normally, IL-10 is considered to have potent anti-inflammatory properties, but increased levels have been reported to be associated with infection." (PMID 36154663, 2022). "Fewer associations with CD4:CD8 ratio > 180 days post infection were observed, with IL-10 and stromal cell-derived factor-1 alpha (SDF-1α) being significant in bivariate analysis." (PMID 35165387, 2022). "In agreement with our previous in vivo report in mice, infection with the P.BCG strain was associated with reduced IL-10 expression." (PMID 35562916, 2022). "The increase in IL-10 can promote a more balanced immune response in these animals, keeping the levels of pro-inflammatory cytokines within ranges compatible with infection control and regulating the inflammation caused by IL-12, IFN-γ, and TNF." (PMID 35154155, 2022).
infection (continued). "Several immunoregulatory molecules and pathways, most notably those associated with IL-10 production, are activated following infection by L. infantum and L. donovani and suppress CD4+ T cell functions." (PMID 35585983, 2022). "High IL‐10 levels in the initial phase of VL lead to susceptibility of infection by decreasing the frequency of multifunctional CD4 T cells." (PMID 35998255, 2022). "The cytokine pattern of IL-6/IL-10 has more remarkable diagnostic precision in bacteremia and severe infection in children with hematological tumors than PCT." (PMID 35463642, 2022). "One of the most important regulatory factors leading to immunodepression and increased infection risk in SAH patients is interleukin 10 (IL-10)." (PMID 35784955, 2022). "On the other hand, it has also been established that the production of IL-6, TGF-β, and IL-10 by macrophages is associated with a poor response to infection." (PMID 36294673, 2022). "In contrast to all measured pro-inflammatory cytokines, the anti-inflammatory cytokine IL-10 was highest in all mice 6 h post infection and had a similar profile in wt and SphK1/2 deficient mice." (PMID 36361636, 2022). "We noticed a significant increase in IL-10 secretion in B.1.1.529 (Omicron) infected MDM compared to infections with the δ-B.1.617 (India) variants (p=0.0244)." (PMID 36601113, 2022). "If the response of anti-inflammatory cytokines such as IL-4 and IL-10 overcompensate for the initial wave of inflammation, it opens susceptibility for future infection or inability to fight the current one." (PMID 35814217, 2022). "IL-10 and IL-12 release is also impaired in human DCs exposed to B. malayi microfilariae; however, pathologies during infection are associated with increased Th1/Th17 responses and enhanced angiogenesis." (PMID 35335634, 2022). "In all trypanosomosis models published so far, the infection-associated excessive production of pro-inflammatory cytokines was shown to be counterbalanced by anti-inflammatory IL-10 response." (PMID 36420267, 2022). "On both days three and five after infection, there were higher percentages and numbers of ILC3s producing IL-17A in the brains of IL-10-deficient mice than WT mice." (PMID 36016413, 2022). "Such IFN-receptor signaling also caused myeloid cell IL-10 production that corrupted antibacterial immunity, leading to loss of infection control and to infection-associated mortality." (PMID 36052075, 2022). "IL-10 knockout mice infected with T. cruzi show increased susceptibility to lethal infection and more significant pathogenic responses associated with pro-inflammatory cytokines." (PMID 35154155, 2022). "The elevated levels of TNF-α in the spleen were associated with the induction of IL-10 expression, which significantly contributed to the establishment of infection." (PMID 34977224, 2021). "The co-expression of IFN-γ and IL-10 by CD4+ T cells has been associated with protective responses induced by vaccination in experimental infection with T. cruzi." (PMID 34868005, 2021). "This is similar to what is observed in gilthead sea bream that become resistant to reinfection with E. leei, where IL-10 is associated with the resolution of infection." (PMID 34578212, 2021). "As an anti-inflammatory factor, IL-10 is vital in protecting the host from tissue damage during acute phases of the immune response toward a pathogenic infection." (PMID 33828554, 2021). "Consistent with us, B cells were reported to have a significant effect on the systemic anaphylaxis caused by infection with S. mansoni, and can inhibit inflammation by secreting IL-10." (PMID 34788282, 2021). "Schistosome specific Th2 responses are downmodulated in long-standing infections and this is associated with a development of regulatory cells producing IL10 and transforming growth factor beta (TGFB)." (PMID 33659002, 2021).
infection (continued). "Concerning IL-10 correlations, this cytokine presented the same participation before and after the infection diagnosis in the susceptible group." (PMID 33617528, 2021). "It is reported that IL-10 plays an essential role in T cell trafficking in various infections caused by parasites like Toxoplasma gondi." (PMID 34305892, 2021). "On the other hand, infection with the less virulent genotype II causes a localized immune response with increased expression of ifnγ, il6, and il10 along with IgM and IgT in the intestine." (PMID 34603313, 2021). "Genotype G/G and G/T of IL-10 rs1800872 were associated with increased risk of infection with influenza A/H3N2 virus." (PMID 33766078, 2021). "Injection of IL-10-deficient mice with exogenous IL-10 at 4 days post-infection (p.i.)greatly reduced morbidity, and all IL-10 recipient mice survived infection." (PMID 33680987, 2021). "High IL-10 levels are mainly associated with active infectious uveitis and are considered to be important in early stages of infection." (PMID 33639877, 2021). "The susceptibility of IgMi−/− mice towards a supposedly resolving acute infection is associated with IL-10 production by B cells during early stages of infection, with dysregulated Th2 responses at later time points of infection." (PMID 33983946, 2021). "For IL10 rs3024496, an association with infections was observed (p = 0.0258, OR 1.63, 95% CI 0.725–3.64)." (PMID 33861738, 2021). "During infection, the generation of Th2 phenotypes, which produce anti-inflammatory cytokines like IL-10, IL-4, TGF-β, is linked to susceptibility whereas induction of pro-inflammatory cytokines producing Th1 phenotypes confers resistance against infection." (PMID 35116028, 2021). "Other factors such as smoking, viruses, and a person’s disease can cause the increase of IL-6, IL-8 and IL-10 in the patient’s body., Our research cannot completely rule out the influence of these factors and other undiagnosed infections." (PMID 34925324, 2021). "The CFU ratio (T48/T0; representing bacterial replication) was indeed associated with the ratio of IFN-γ divided by IL-10 in response to infection." (PMID 33510265, 2021). "Significant associations between SNVs on IL21R and infection with A. lumbricoides and levels of anti-Ascaris lumbricoides IgE and IgG4 and parasite antigen induced production of IL-5 and IL-10 by PBLs." (PMID 33692795, 2021). "By suppressing the pro-inflammatory response caused by various immune cells, IL-10 limits tissue damage and immunopathology caused during infection." (PMID 34925324, 2021). "In fact, during pathogen infection, early cytokines responses involving IL-4 and IL-10 increase host susceptibility, whereas responses involving IL-12 and IFN-γ are important for resistance." (PMID 34035796, 2021). "Polymorphisms in the IL-10 gene or increased IL-10 production can increase host susceptibility to a wide variety of infections in humans and in animal models." (PMID 34960620, 2021). "The data above indicate that Spn infection drives the production of IL-10 by NK cells to increase susceptibility to oral Lm infection." (PMID 33878120, 2021). "What’s more, either SARS-CoV-2 or it’s variants infection, Meplazumab treatment had a favorable therapeutic effect on the downregulation of cytokines and chemokines at 6 d.p.i., such as IL-6, IL10, IL1b, CCL2, CXCL1, CXCL2, IFN-γ, IL-17, and CyPA." (PMID 34564690, 2021). "The IL-10-819 TT genotype is potentially protective against infection through its association with lower IL-10 levels." (PMID 34007813, 2021). "In fact, the augmentation of the liver expression of the regulatory cytokine IL-10 argues in favour of such an underlying regulatory immune network paralleling prolonged/repeated exposure to infection in our setting." (PMID 34956183, 2021).